FOXO3B (forkhead box O3B)
Description:
Transcription factor.
Synonyms: FKHRL1P1; ZNF286C
Gene: Protein-coding gene on chromosome 17 (18,667,629 to 18,682,314, reverse strand). Ensembl gene ENSG00000240445.
Subcellular location: Cytoplasm, cytosol
Gene Ontology:
Molecular function: DNA-binding transcription factor activity, RNA polymerase II-specific; RNA polymerase II cis-regulatory region sequence-specific DNA binding; DNA-binding transcription factor activity; sequence-specific DNA binding
Biological process: regulation of transcription by RNA polymerase II; response to starvation; regulation of DNA-templated transcription
Cellular component: mitochondrial matrix; nucleus; cytosol
Genetic constraint (gnomAD): Loss-of-function variants: 15 observed, 15.76 expected, observed/expected ratio (o/e) 0.95, 90% interval 0.64 to 1.46. The upper end of that interval is the gene's LOEUF score, 1.46, which puts it in group 6 of 6, group 1 being the genes least tolerant of losing a copy. Missense variants: 290 observed, 318.02 expected, observed/expected ratio (o/e) 0.91, 90% interval 0.83 to 1. Synonymous variants: 135 observed, 142.77 expected, observed/expected ratio (o/e) 0.95, 90% interval 0.82 to 1.09.
Diseases named in the same sentence as FOXO3B in open-access papers:
FOXO3B is named in the same sentence as 3 diseases in open-access papers, as found by Europe PMC text mining. Sharing a sentence is not in itself a finding about the gene and the disease. The quoted sentences say what the papers report.
infection (1 paper, 2019). The state of being infected such as from the introduction of a foreign agent such as serum, vaccine, antigenic substance or organism. "In a first study, foxo3b−/− mutant zebrafish larvae were generated, and exhibited an increased resistance to infection with spring viremia of carp virus (SVCV), with the expression level of viral genes found to be lower than in the wild-type larvae." (PMID 30917538, 2019). "In other hands, the over-expression of foxo3b reduced the induction levels of ISGs following stimulation with a synthetic dsRNA (poly I:C) or SVCV infection." (PMID 30917538, 2019).
FOXO3B also shares sentences with these, for which no sentence is quoted: hepatocellular carcinoma (1 paper); liver cancer (1).